EPB41L4A-AS1 (EPB41L4A antisense RNA 1)
Synonyms: EAS1; TIGA1; formerly C5orf26; NCRNA00219
Gene: Long non-coding RNA gene on chromosome 5 (112,160,526 to 112,164,818, forward strand). Ensembl gene ENSG00000224032.
Gene Ontology:
Biological process: RNA processing
Cellular component: nucleolus
Diseases named in the same sentence as EPB41L4A-AS1 in open-access papers:
EPB41L4A-AS1 is named in the same sentence as 5 diseases in open-access papers, as found by Europe PMC text mining. Sharing a sentence is not in itself a finding about the gene and the disease. The quoted sentences say what the papers report.
infection (2 papers, 2021 to 2025). The state of being infected such as from the introduction of a foreign agent such as serum, vaccine, antigenic substance or organism. "Through transcriptomic analysis, we identified that the lncRNA EPB41L4A-AS1 (EAS1) is consistently upregulated upon infection by multiple coronaviruses, including SARS-CoV-2, SARS-CoV, MERS-CoV, and HCoV-229E." (PMID 41093073, 2025).
cancer (1 paper, 2019). A tumor composed of atypical neoplastic, often pleomorphic cells that invade other tissues. "EPB41L4A‐AS1 (also known as TIGA1) has been shown to be transcribed during growth arrest but has not been extensively studied in cancer to elucidate its role." (PMID 30959550, 2019).
EPB41L4A-AS1 also shares sentences with these, for which no sentence is quoted: COVID-19 (1 paper); lung carcinoma (1); viral infection (1).